ALK (ALK receptor tyrosine kinase)
Diseases named in the same sentence as ALK in open-access papers (continued):
Sharing a sentence is not in itself a finding about the gene and the disease.
inflammatory myofibroblastic tumor (220 papers, 2010 to 2026). A multinodular intermediate fibroblastic neoplasm that arises from soft tissue or viscera, in children and young adults. "Other notable targets being investigated in the STS realm include NTRK fusion in CD34-positive fibrosarcomas of bone and soft tissue, EZH2/INI1 loss (epithelioid sarcomas, rhabdoid tumors), and ALK fusion in inflammatory myofibroblastic tumors." (PMID 40075735, 2025). "Inflammatory myofibroblastic tumors (IMTs) are known to be associated with rearrangements of the anaplastic lymphoma kinase (ALK) gene." (PMID 39931211, 2024). "Epithelioid inflammatory myofibroblastic sarcoma (EIMS) is a rare variant of the inflammatory myofibroblastic tumor, characterized by more aggressive clinical course and nuclear membrane staining of anaplastic lymphoma kinase (ALK) with ALK rearrangement." (PMID 37841422, 2023). "Inflammatory myofibroblastic tumors (IMTs) are known to be associated with anaplastic lymphoma kinase (ALK) gene rearrangements." (PMID 36035049, 2022). "The fibrohistiocytic type of IPT is frequently misdiagnosed as inflammatory myofibroblastic tumor, which is associated with ALK." (PMID 36484868, 2022). "The only exception is the inflammatory myofibroblastic tumor presenting the ALK gene mutation, which is susceptible to ALK inhibitors." (PMID 32722580, 2020). "EIMS represents a highly aggressive variant of inflammatory myofibroblastic tumor characterized by epithelioid morphology, prominent neutrophilic infiltrate, and nuclear membrane staining of ALK with ALK rearrangement." (PMID 27460384, 2016). "Powerful prognostic data also is emerging such as in inflammatory myofibroblastic tumor with ALK rearrangements and possibly CTNNB1 mutations in desmoids." (PMID 21403834, 2011). "Inflammatory myofibroblastic tumors (IMT) were the first solid tumor to be associated with ALK translocation." (PMID 29455642, 2018). "The Inflammatory myofibroblastic tumor (IMT) is associated with rearrangements of the ALK (anaplastic lymphoma kinase) locus on chromosome 2p23.13." (PMID 27905051, 2016). "In inflammatory myofibroblastic tumors (IMTs), ALK aberrations primarily involve gene rearrangements, with ALK fusions detected in approximately 50–60% of cases." (PMID 41614760, 2025). "The development of targeted therapies with ALK inhibitors has shown positive outcomes in many tumor types, including other sarcomas such as inflammatory myofibroblastic tumors, where ALK inhibitors have shown benefits." (PMID 40361368, 2025). "At the local hospital, the patient was initially considered to have an ALK-positive intestinal tumor, leading to a differential diagnosis of inflammatory myofibroblastic tumor (IMT)." (PMID 40224190, 2025). "Anaplastic lymphoma kinase (ALK) gene rearrangement is present in approximately 50% of inflammatory myofibroblastic tumors (IMTs), which are rare mesenchymal tumors primarily affecting pediatric and adolescent populations." (PMID 40075735, 2025). "These include ALK fusions in inflammatory myofibroblastic tumors, COLIA1-PDGFB fusions in dermatofibrosarcoma protuberans and INI1/SMARCB1 mutations/deletions in epithelioid sarcoma." (PMID 40505420, 2025). "Although initially considered reactive, recent findings of clonal cytogenetic abnormalities and anaplastic lymphoma kinase (ALK) expression in inflammatory myofibroblastic tumors (IMTs) suggest a neoplastic origin for some lesions." (PMID 40964556, 2025). "LRRFIP1 has been implicated in 8p11 myeloproliferative syndrome through its fusion with FGFR1, in inflammatory myofibroblastic tumors with ALK and in atypical Spitz tumors with MET." (PMID 38338888, 2024). "In summary, we presented a rare case of long-responder musculoskeletal inflammatory myofibroblastic tumor with ALK rearrangement and metastatic evolution." (PMID 39931211, 2024).
inflammatory myofibroblastic tumor (continued). "Epithelioid inflammatory myofibroblastic sarcoma (EIMS), a variant of inflammatory myofibroblastic tumor (IMT), is a rare malignant tumor commonly associated with anaplastic lymphoma kinase (ALK) gene fusions and is aggressive in nature with local recurrence." (PMID 39347189, 2024). "Differential diagnoses that should be considered include breast cancer, myxoma, fibroma, ALK-positive histiocytosis, and IgG4-related inflammatory pseudotumor." (PMID 37656266, 2023). "The abnormal expression of ALK led to the initial misdiagnosis of an inflammatory myofibroblastic tumor." (PMID 37114141, 2023). "Various histological subtypes of STS have been associated with specific genetic fusions, such as SS18::SSX in synovial sarcoma, FUS::DDIT3 in myxoid liposarcoma, and TMP4::ALK in inflammatory myofibroblastic tumor." (PMID 36980578, 2023). "The FN1::FGFR1 fusion gene is detected in phosphaturic mesenchymal tumors with paraneoplastic osteomalacia and FN1 has also been recently described as a novel fusion partner of ALK in an inflammatory myofibroblastic tumor." (PMID 36439507, 2022). "Inflammatory myofibroblastic tumors are another rare malignancy that frequently harbor ALK or ROS1 translocations." (PMID 35233056, 2022). "We identified seven patients (inflammatory myofibroblastic tumors, n = 3; ALK-positive histiocytosis, n = 1; histiocytic sarcoma, n = 1; osteosarcoma, n = 1; and parotid adenocarcinoma, n = 1), with a median age of 17 years." (PMID 34036223, 2021). "ALK translocation has also been discovered in rare tumors called inflammatory myofibroblastic tumors (IMTs)." (PMID 34209967, 2021). "The sarcomatoid variant of ALK- ALCL should be distinguished from sarcomatoid carcinoma, high grade spindle cell sarcomas, and inflammatory pseudotumor." (PMID 34572893, 2021). "For example, certain rearrangements, such as those involving ALK in inflammatory myofibroblastic tumors or COL1A1-PDGFB in dermatofibrosarcoma protuberans, are predictive of the response to tyrosine kinase inhibitors." (PMID 32351889, 2020). "Six patients with inflammatory myofibroblastic tumors developed local recurrence after the administration of ALK tyrosine kinase inhibitors." (PMID 33362974, 2020). "Nine patients (15.7%) with inflammatory myofibroblastic tumors received ALK tyrosine kinase inhibitors." (PMID 33362974, 2020). "Before anaplastic lymphoma kinase (ALK) inhibitors, treatment options for ALK-positive inflammatory myofibroblastic tumors (AP-IMTs) were unsatisfactory." (PMID 32914017, 2019). "Key Objective To document the long-term outcome of a cohort of children and teenagers diagnosed with widespread, multifocal, ALK-positive inflammatory myofibroblastic tumors (AP-IMTs) treated in a crizotinib compassionate use access program." (PMID 32914017, 2019). "It was approved by the Food and Drug Administration for the treatment of ALK-positive non-small-cell lung cancer and inflammatory myofibroblastic tumors." (PMID 31278140, 2019). "Inflammatory myofibroblastic tumor is a rare neoplasm that harbors an ALK gene rearrangement in the majority of cases." (PMID 29137037, 2017). "Approximately half of the inflammatory myofibroblastic tumors contain translocations that result in the over-expression of the anaplastic lymphoma kinase (ALK) gene." (PMID 28409069, 2017). "Inflammatory myofibroblastic tumors are rare mesenchymal neoplasms frequently harboring oncogenic chromosomal rearrangements, most commonly, involving the ALK (anaplastic lymphoma kinase) gene." (PMID 29872693, 2017). "ALK positivity in inflammatory myofibroblastic tumors in patients above the age of 25 is relatively infrequent." (PMID 28018701, 2016). "Approximately half of inflammatory myofibroblastic tumors present rearrangements of the locus of the anaplastic lymphoma kinase (ALK) gene on chromosome 2p23, resulting in the aberrant expression of ALK." (PMID 24714847, 2014).
inflammatory myofibroblastic tumor (continued). "We present the first reported case, to our knowledge, of inflammatory myofibroblastic tumor with systemic manifestations and ALK translocation." (PMID 25045570, 2014). "In summary, this case represents a distinct presentation of inflammatory myofibroblastic tumor with systemic involvement and ALK gene rearrangement." (PMID 25045570, 2014). "A partial response by the inhibitor of ALK, crizotinib, has been reported in a patient with inflammatory myofibroblastic tumor with ALK translocation." (PMID 24714847, 2014). "ALK rearrangements are also observed in inflammatory myofibroblastic tumors." (PMID 40904239, 2025). "Therefore, identifying ALK-positive findings through immunohistochemistry or fluorescent in situ hybridization is crucial for accurately diagnosing an inflammatory myofibroblastic tumor." (PMID 39085476, 2025). "Since 2/3 of AFH and epithelioid EWSR1::CREB-rearranged malignant neoplasms may express ALK protein, an epithelioid inflammatory myofibroblastic tumor (IMT) is a major differential diagnosis." (PMID 37097347, 2023). "However, ALK gene rearrangements have been described in 50% of inflammatory myofibroblastic tumors, a mesenchymal neoplasm, and therefore relevant to the subject of this review." (PMID 36980578, 2023). "The inflammatory myofibroblastic tumor revealed ALK expression." (PMID 35001360, 2022). "Similarly, crizotinib also showed therapeutic responses in ALK-fusion-positive inflammatory myofibroblastic tumor (IMT) patients and paediatric patients with ALCL and IMT." (PMID 33466277, 2021). "ALK positivity occurs in about 50% of cases of inflammatory myofibroblastic tumors." (PMID 26762155, 2016). "Interestingly, ALK fusions have also been described in anaplastic lymphomas and in about 50% of inflammatory myofibroblastic tumors (IMTs) with EML4." (PMID 22363766, 2012). "Preoperative bladder biopsy pathology indicated an inflammatory myofibroblastic tumor (IMT), with immunohistochemistry (IHC) showing Ki-67 positivity (hotspot area 20%) and positivity for anaplastic lymphoma kinase (ALK)." (PMID 39980542, 2025). "In terms of differential diagnosis, the most important entities are represented by inflammatory myofibroblastic tumor (IMT) that is ALK-positive in about 50% of cases and also low-grade myofibroblastic sarcoma, which usually is more infiltrative." (PMID 39070491, 2024). "Nuclear expression of beta-catenin for desmoid fibromatosis and ALK expression for inflammatory myofibroblastic tumor (IMT) are also useful to distinguish GIST." (PMID 38609732, 2024). "Inflammatory myofibroblastic tumor (IMT) is a distinctive tumor composed of spindle cells accompanied by mixed inflammatory cells, and immunohistochemical positivity for ALK (anaplastic lymphoma kinase protein) can be detected in half of IMTs." (PMID 37735390, 2023). "However, these mutations are genetic aberrations at the mRNA level in the specific domain of the ALK gene, and they are different from the ALK-related translocations observed in NSCLCs and inflammatory myofibroblastic tumors as we will discuss below in Section 2.7." (PMID 30487384, 2018). "Another tropomyosin gene, TPM4, has also been found to be fused to the ALK gene in inflammatory myofibroblastic tumors (IMT) and other tumors." (PMID 25888090, 2015). "While most histologically-defined tumor types have one of these mutation types, a few like the inflammatory myofibroblastic tumor (IMT) and NSCLC can have ALK mutations in two categories." (PMID 24955213, 2014). "Further IHC (H caldesmon, Desmin, DOG-1, and ALK) were done for confirmation and to rule the close differentials like Angioleiomyoma, GIST and Inflammatory myofibroblastic tumor." (PMID 40043410, 2025). "Here, we described an extremely rare case of EML4::ALK positive pulmonary PLC with intestinal metastasis, which histologically mimics inflammatory myofibroblastic tumor (IMT)." (PMID 40224190, 2025).
inflammatory myofibroblastic tumor (continued). "Notably, EML4::ALK fusions are common due to inflammatory myofibroblastic tumor (IMT) occurring in the lung." (PMID 39867882, 2024). "Since the initial discovery of the NPM–ALK fusion protein in ALCL patients, ALK fusion proteins have been identified in various other tumors, such as inflammatory myofibroblastic tumors (IMTs) and non-small-cell lung cancer (NSCLC)." (PMID 38339401, 2024). "TPM3-ALK and TPM4-ALK, a fusion protein consisting of the N-terminal of TPM and the C-terminal kinase domain of ALK, have been reported in patients with inflammatory myofibroblastic tumors, with TPM3-ALK being the most commonly observed." (PMID 37686101, 2023). "In solid tumors, ALK rearrangements including TPM4-ALK and TPM3-ALK have been identified in up to 50-75% of inflammatory myofibroblastic tumors (IMT)." (PMID 35233056, 2022). "Inflammatory myofibroblastic tumor (IMT) is a very rare subtype of sarcoma, which frequently harbor chromosomal rearrangements, including anaplastic lymphoma kinase (ALK) rearrangements (almost 50% of the IMTs) and other kinase fusions such as ROS1." (PMID 34211840, 2021). "Inflammatory myofibroblastic tumor (IMT), which consists of rare components of STS, harbors specific fusion genes including ALK, and TKIs inhibiting ALK showed high responses to ALK-arranged IMT in prospective clinical trials." (PMID 31963219, 2020). "TPM3-ALK and TPM4-ALK, which are fusion proteins consisting of the N-terminus of TPM and the C-terminal kinase domain of ALK, have been reported in patients with inflammatory myofibroblastic tumors, with TPM3-ALK being the most frequently observed." (PMID 31278140, 2019). "Available clinical data does not as yet support any conclusion about the development of therapy resistance in children on continuous treatment for ALK-fusion positive tumors, although case reports exist in the inflammatory myofibroblastic tumor (IMT) literature." (PMID 27483357, 2016). "Among them, huntingdon-interacting protein (HIP1)-ALK and RAN-binding protein 2 (RANBP2)-ALK, which have been reported to exist in NSCLC and inflammatory myofibroblastic tumors, respectively, show clinical responses to crizotinib." (PMID 26295973, 2015). "In the present case, the differential diagnosis should have included inflammatory myofibroblastic tumor (IMT), a typical neoplastic entity with positive immunostaining of ALK." (PMID 25487870, 2014). "While some ALK-altered mesenchymal neoplasms can be classified into defined WHO categories (e.g., inflammatory myofibroblastic tumor, epithelioid fibrous histiocytoma, and a few others), the nosology of many tumors has not yet been delineated, and they are currently reported descriptively." (PMID 42311268, 2026). "Similarly, ALK/ROS1 inhibitors (crizotinib, ceritinib) demonstrate efficacy in inflammatory myofibroblastic tumors (IMTs), NSCLC, and renal cell carcinomas (RCCs) harboring TPM3‐ALK/ROS1 fusions." (PMID 41275415, 2025). "Inflammatory myofibroblastic tumor, another potential differential diagnosis, was ruled out as it is typically ALK-positive, and the current tumor was ALK-negative." (PMID 39857780, 2025). "The histological differential diagnosis of CMN includes metanephric stromal tumor (CD34 positive), stromal type Wilms tumor (WT-1 positive), and inflammatory myofibroblastic tumor (ALK-positive), all of which were negative in our case." (PMID 39493139, 2024). "Most inflammatory myofibroblastic tumors stain positive for desmin, smooth muscle actin, and anaplastic lymphoma kinase (ALK), whereas this patient was non-immunoreactive." (PMID 37123715, 2023). "Actionable kinase fusions in sarcoma have not been comprehensively described with the exception of ALK fusions in inflammatory myofibroblastic tumors (IMT) and NTRK1–3 fusions in infantile fibrosarcoma." (PMID 35705558, 2022).
inflammatory myofibroblastic tumor (continued). "The patient underwent surgical resection of the mass and a pathological examination confirmed the lesion to be an inflammatory myofibroblastic tumor with negative expression of anaplastic lymphoma kinase (ALK)." (PMID 36460992, 2022). "An inflammatory pseudotumor can be positive or negative for ALK (~50% of cases), positive for SMA, and is negative for desmin, CD30, and T-cell markers (highlight background small T-cells)." (PMID 34572893, 2021). "Inflammatory myofibroblastic tumor with RANBP2 and ALK gene rearrangement." (PMID 32847129, 2020). "Negative results for DOG-1, CD117 (KIT), CD34, S-100 protein, neurofilament, cytokeratin, epithelial membrane antigen (EMA), and ALK suggest that PF is a distinct disease entity from GIST, angiomyxoma, neurogenic tumor, sarcomatoid carcinoma, and inflammatory myofibroblastic tumor." (PMID 31360694, 2019). "More therapies targeted to specific fusion gene/proteins have been emerging; anaplastic lymphoma kinase (ALK) is well known as a treatment target of non-small cell lung cancer, and ALK-related fusion gene is also observed in an paricular STS, i.e., inflammatory myofibroblastic tumor (IMT)." (PMID 29510588, 2018). "In addition, ALK and ROS1 fusions are highly characteristic for inflammatory myofibroblastic tumors (IMT)." (PMID 30211169, 2018). "Inflammatory myofibroblastic tumor (IMT) was the first non-hematological tumor found to harbor ALK rearrangements in about 50% of cases." (PMID 29495603, 2018). "Indeed, since the identification of NPM–ALK and other ALK fusions as oncogenes for ALCL and inflammatory myofibroblastic tumors, several pharmaceutical companies developed ALK-specific TKIs." (PMID 25950466, 2015). "Although the tumor cells were negative for ALK, the histologic appearance was characteristic of an inflammatory myofibroblastic tumor." (PMID 26445324, 2015). "Interestingly, this translocation has been described in less than 1% of cases of ALK+ ALCL and has also been identified in inflammatory myofibroblastic tumors (IMT)." (PMID 22474449, 2012). "Additionally, the detection of a TFG::ROS1 fusion in an ALK-negative inflammatory myofibroblastic tumor and the neoadjuvant use of crizotinib in that patient demonstrate the expanding relevance of targeted therapies in pediatric pulmonary malignancies." (PMID 40868080, 2025). "Although ALK immunoreactivity was negative in this case, the possibility of an inflammatory myofibroblastic tumor could not completely be excluded." (PMID 26762155, 2016). "Although crizotinib is initially approved as a targeted therapy for NSCLC, a study focusing on inflammatory myofibroblastic tumors reported a partial response to it in a patient with ALK translocation, while there was no observed activity in another patient without the translocation." (PMID 26678488, 2015). "ALK-related diseases comprise a diverse set of malignancies, including subsets of non-small cell lung cancer (NSCLC), anaplastic large-cell lymphoma (ALCL), inflammatory myofibroblastic tumor (IMT), neuroblastoma, as well as breast, colon and thyroid cancers, and other rarer diseases." (PMID 25749034, 2015). "Inflammatory myofibroblastic tumors (IMTs) are categorized as intermediate biologic neoplasms, whereas IMTs with genetic features of ran-binding protein 2 (RANBP2) and anaplastic lymphoma kinase (ALK) rearrangement (IMT-RAs) are possibly related to a more aggressive clinical course." (PMID 24034896, 2013). "Aberrant activation of ALK was first described in anaplastic large cell lymphoma (ACLC) and in inflammatory myofibroblastic tumor (IMT)." (PMID 21785682, 2011). "The translocation of chromosomes including the ALK gene has been demonstrated in various cancers including anaplastic large‐cell lymphoma (ALCL), non‐small cell lung cancer (NSCLC), and inflammatory myofibroblastic tumors (IMT)." (PMID 33040459, 2021).